AHR (aryl hydrocarbon receptor)
Diseases named in the same sentence as AHR in open-access papers (continued):
Sharing a sentence is not in itself a finding about the gene and the disease.
breast carcinoma (continued). "Indeed, the evaluation of an ER+ breast cancer cohort with a 10‐year follow‐up (Table EV6), identified increased AHR, DDA1, and UBE4B levels in the primary tumors that relapsed (EV4O and Q, Table EV7)." (PMID 35174975, 2022). "In in vitro studies, AhR was demonstrated to cooperate with the Rb tumor suppressor to prevent S-phase cell cycle entry while activation of AhR by the prototypical ligand TCDD inhibited the growth of MCF7 breast cancer cells." (PMID 36588678, 2022). "In MCF-7 breast cancer cells in a mouse xenograft model, AhR expression was not required for mammary tumorigenesis." (PMID 36428667, 2022). "I3C also binds the AhR with lower affinity than DIM and I3C inhibits breast cancer cell growth and migration; some of this activity may be due to the facile conversion of I3C into DIM." (PMID 36428667, 2022). "The aryl hydrocarbon receptor (AhR) is overexpressed in many breast tumor sub-types, including estrogen receptor -positive (ER+) tumors; however, the prognostic value of the AhR for breast cancer patient survival is not consistent between studies." (PMID 36428667, 2022). "AhR is also expressed in the liver and intestinal tract of pigs, and crosstalk between AhR and PXR was previously found to mediate the cytostatic properties of IPA in breast cancer cells." (PMID 36144190, 2022). "The aryl hydrocarbon receptor (AhR) is expressed in breast cancer cells and tumors and in some studies, the AhR is a negative prognostic factor for patient survival." (PMID 36428667, 2022). "In Hs578T (triple negative) and SUM149 (inflammatory) breast cancer cells, AhR was shown to augment the BCSC population, and its inhibition decreased tumor growth and sensitized cells to both adriamycin and paclitaxel." (PMID 36588678, 2022). "In our recent study we demonstrated that overexpression of AhRR (Aryl Hydrocarbon Receptor Repressor) suppresses AhR-driven (TCDD-stimulated) growth of syngeneic mammary tumors as well the onset, growth and metastasis of spontaneous mammary tumors in PyMT mice." (PMID 36588678, 2022). "The results show that several AhR agonists, including TCDD, 3,31,4,41-tetrachlorobiphenyl (TCBP), diindolylmethane (DIM) and substituted DIM analogs, and 6-methyl-1,3,8-trichlorodibenzofuran (MCDF) inhibit the formation and growth of mammary tumors." (PMID 36428667, 2022). "The purpose of this study was to elucidate the interplay between intratumoral levels of AhR and aromatase, patient characteristics (including AhR and CYP19A1 genotypes), clinicopathological features, and prognosis in breast cancer patients receiving adjuvant treatments." (PMID 34094928, 2021). "Similarly, AhR can reactivate the LINE-1 retro-transposon, silenced by DNA methylation, in breast cancer via the regulation of TGF-β signaling, promoting tumorigenesis and disease progression." (PMID 33451095, 2021). "Therefore, the accumulation of the anti-AhR activity from LUT and I3C contributes to the ERα level and then inhibits ER+ breast cancer cell growth." (PMID 33925607, 2021). "While the repressor protein of the AhR (AhRR) blocks the canonical AhR pathway, the function of AhRR in the development of breast cancer is not well-known." (PMID 33763068, 2021). "BRM and BRG1 mediate chromatin remodeling by binding to AHR target loci and recruiting steroid receptor coactivator 1 (SRC-1), steroid receptor coactivator 2 (SRC-2) and p300, a nuclear receptor coactivator in breast cancer cells." (PMID 34698116, 2021). "In addition, high doses of AhR ligand aminoflavone (AF) acts as an AhR antagonist, inhibiting Src-Akt signaling and suppressing α6-integrin expression to attenuate tamoxifen-resistance in MCF-7 breast cancer cells." (PMID 33451095, 2021). "For instance, AhR exerts the proteasome-dependent degradation of ERα proteins by binding its ligands, including 2-, 3-, 7-, 8-tetrachlorodibenzo-p-dioxin in MCF-7 human breast cancer cells." (PMID 33925607, 2021).
breast carcinoma (continued). "We assessed whether the expression of AHR and PXR correlates with survival in human breast cancer using the kmplot.com database." (PMID 32854297, 2020). "The expression level of AHR did not have a clear impact on breast cancer survival; nevertheless, there was a trend for better survival in the high expression quartile, similarly to the RNAseq data." (PMID 32854297, 2020). "Overall, emodin may exhibit anti-tumor activity by activating the AhR/CYP1A1 pathway, which lays the foundation for the application of emodin in breast cancer treatment." (PMID 33542691, 2020). "As the cross-talk between AhR and ERα has been well documented at the transcriptional level, we investigated the activation of the AhR reporter gene by the glyceollins in both ER-positive MCF-7 and ER-negative MDA-MB-231 breast cancer cells." (PMID 32085612, 2020). "The complex mechanism of action between AhR/CYP1A1 and breast cancer still requires further study." (PMID 33542691, 2020). "Supporting previous data highlighted that in the ERα-negative/triple negative context, an AhR-signaling reinforces cell aggressiveness and induces breast cancer stem cells." (PMID 32670863, 2020). "Altogether, our data reveal a new/original signature based on a combination of high AhR mRNA expression levels and high GPR30 mRNA expression levels that represents a novel marker for poor prognosis in breast cancer, especially in ER-negative or triple-negative subclasses." (PMID 32670863, 2020). "Moreover, EGFR has been reported to interact with AHR and GPER (G protein estrogen receptor) to stimulate breast cancer progression and EGFR can bypass RhoA to activate YAP signaling to promote hepatocellular carcinoma proliferation." (PMID 32546278, 2020). "To illustrate this point in cancer cells here, we generated CYP1B1 knockout SUM149 inflammatory breast cancer cells and quantified AHR activity in the presence or absence of AHR agonists using an AHR-driven (pGudLuc) reporter construct." (PMID 33396563, 2020). "Considering the involvement of GPER in the multifaceted actions exerted by estrogens and environmental contaminants, in the present study we aimed to provide novel insights on the ability of 3MC to elicit stimulatory effects through both AHR and GPER in breast cancer cells and CAFs." (PMID 31370872, 2019). "In the present study we have provided novel insights regarding the molecular mechanisms by which 3MC may trigger a physical and functional interaction between AHR and GPER, leading to the stimulation of both SkBr3 breast cancer cells and CAFs." (PMID 31370872, 2019). "AHR mRNA levels in breast cancers were not a prognostic factor for patient survival, as also reported for colon, pancreas, stomach and thyroid cancers, which express high AHR mRNA levels." (PMID 29320557, 2018). "Identification of phosphorylated receptors in human tumors and discovery of phospho-PR-regulated pathways (i.e., including HER2, RUNX2, AR, AHR, and PAX2) suggest novel ways to specifically target breast cancer stem cell (CSC) outgrowth as part of durable breast cancer therapies." (PMID 28412963, 2017). "To address this point, we examined the effects of two well-known AhR agonists and potent CYP1A1 inducers, TCDD and DMBA, on mammosphere formation numbers as an indicator of increased or decreased in the self-renewal capacity of breast cancer cells." (PMID 28103884, 2017). "To test our hypothesis, we initially investigated the constitutive expression of AhR and its regulated genes, CYP1A1 and CYP1B1 in different breast cancer cell lines." (PMID 28103884, 2017). "AHR also regulates various stem cell lineages, and promotes BCSC populations in tamoxifen-resistant breast cancer cells but not in susceptible cells." (PMID 27129165, 2016). "Importantly, the expression of the AhR and downstream gene targets such as CYP1B1 are increased in human and rodent mammary tumors." (PMID 26715507, 2015).
breast carcinoma (continued). "In addition to increasing CYP1A1/1A2/1B1 expression, AF induces nuclear translocation of AhR and stimulates protein-DNA complexes formed on DREs in AF-sensitive MCF7 human breast cancer cells, suggesting that AF is an AhR agonist." (PMID 24885022, 2014). "Our initial studies investigated the AHR agonist activities of eight AHR-active pharmaceuticals including tranilast and 4-hydroxytamoxifen in MDA-MB-468 and BT474 breast cancer cells and observed that their AHR activity was structure-, cell context- and response-specific." (PMID 25011475, 2014). "Furthermore, Vogel and colleagues showed that TCDD induced dimerization of AhR and RelB of the alternative NF-κB pathway and up-regulation of CXCL8 through a novel RelB/AhR response element (RelBAHRE) in macrophages and breast cancer cells." (PMID 25201625, 2014). "In summary, results of this study demonstrate that among several AHR-active pharmaceuticals, omeprazole exhibits antimetastatic activity for triple-negative MDA-MB-231 breast cancer cells, and CXCR4 is one of the key target genes not only for omeprazole but also for other AHR agonists." (PMID 25011475, 2014). "Aryl hydrocarbon receptor (AHR) ligands show promise as antimetastatic drugs for estrogen receptor (ER)-negative breast cancer." (PMID 25011475, 2014). "Here, we focus on recent advances in the understanding of molecular mechanisms that mediate this crosstalk repression, and particularly on how ERα represses the AhR target gene CYP1A1, and could subsequently promote breast cancer." (PMID 25257533, 2014). "A constitutively active mutant of AhR that was designed to mimic continuous TCDD activation also inhibited expression of estrogen-dependent cathepsin D and attenuated the estrogen-induced growth of MCF-7 human breast cancer cells." (PMID 25068070, 2013). "It was suggested that anti-tumorigenic effects of I3C in MCF7 human breast cancer cells may arise from its ability to reduce ERα expression through the binding of its metabolite, DIM to nuclear AhR." (PMID 23090135, 2013). "Therefore, we sought to determine the specific functions of AHR and ARNT in estrogen-dependent signaling in human MCF7 breast cancer and human ECC-1 endometrial carcinoma cells." (PMID 22235307, 2012). "The AhR was found to be overexpressed in primary breast cancers and mammary tumor cell lines in the absence of detectable xenobiotics and there is convincing evidence for a critical role of endogenous AhR in proliferation control in tumor cells." (PMID 20565777, 2010). "These scientists consider that in these cases, AhR itself must be playing the important tumor promoting roles in the development of mammary tumors even without the aid of its exogenous ligand." (PMID 19604390, 2009). "We found no reports on AHR genotypes and smoking or alcohol in breast cancer." (PMID 40646277, 2025). "None of the AHR SNPs interacted with adjuvant chemotherapy regarding breast cancer events." (PMID 40646277, 2025). "Hence, TCDD may inhibit growth factor-driven EGFR signal transduction in early stages of breast cancer, whereas it is probably ineffective in doing so in advanced stages, when TCDD-activated AHR may dominate and drive tumor progression." (PMID 39996234, 2025). "Additionally, camalexin inhibited mammosphere formation in AhR-expressing breast cancer cells more than in the breast cancer cells that lacked AhR expression." (PMID 38792249, 2024). "Furthermore, in ER-negative MDA-MB-231 and BT-549 breast cancer cells, resveratrol (10 μM) suppressed AhR-dependent transcription, suggesting that ERα was not involved in resveratrol’s AhR-inhibiting effects." (PMID 39339278, 2024). "Considering that AhR/ER crosstalk established for estrogen receptor-positive (ER+) cells and that AhR agonist might be used as a cancer therapeutics opens new possibilities to the medical need for therapy for estrogen receptor-negative (ER‒) breast cancers." (PMID 37633886, 2023).
breast carcinoma (continued). "Many triple-negative breast cancers (TNBCs) express high levels of AhR, and in patients with ER+ or ER-/PR- breast cancers, higher expression levels of AhR correlated with improved relapse-free survival relative to ER- and PR-negative cancers with a low expression of AhR." (PMID 37106727, 2023). "Importantly, the AhR has been demonstrated to regulate the expression of immune-regulatory markers including Arg1, IDO, IL-10, COX-2, C/EBPβ, and S100A9, which are critical factors in the pathogenesis of breast cancer." (PMID 36588678, 2022). "Moreover, overexpression of CYP1B1 is not known to activate the AHR, and treatment of breast cancer cell lines with 4-hydroxyestradiol, the primary estrogen product of CYP1B1, results in effects similar to ectopic CYP1B1 expression." (PMID 36077068, 2022). "Interestingly, AhR as well as NFkB RelB have been shown to induce IDO expression, which is also critically involved in the immunosuppressive mechanisms of myeloid-derived suppressor cells (MDSCs) in breast cancer." (PMID 36588678, 2022). "In addition to ER-agonist, this phytoconstituent was known as AHR-antagonist (aryl hydrocarbon receptor), which was related to the inhibition activity on transcription of AHR in ER-α-negative breast cancer cell lines independent of ER-α expression." (PMID 35986346, 2022). "Considering that AhR has recently emerged as a physiological regulator of the innate and adaptive immune responses, in a previous publication we described that AFP 464 modulates the immune response in the estrogen-dependent, Tamoxifen-sensitive spontaneous M05 mammary carcinoma model." (PMID 32443455, 2020). "Overall, our data demonstrated that FICZ, as an AhR agonist could induce the expression of tumorsuppressor miRNAs, miR-22, miR-515-5p, and miR-124-3p; thus, FICZ might be regarded as a potential therapeuticagent for breast cancer treatment." (PMID 31606975, 2020). "Here, we have provided novel insights on the crosstalk that may occur between AHR and GPER upon exposure to 3MC, toward the up-regulation of CYP1B1 and cyclin D1 expression as well as the proliferative effects observed in breast cancer cells and main components of the tumor microenvironment as CAFs." (PMID 31370872, 2019). "Moreover, rodent and human mammary tumors overexpress constitutively active AHR, which is characterized by elevated CYP1B1 but not CYP1A1 mRNA." (PMID 31652854, 2019). "The levels of AHR, AHR nuclear translocator (ARNT) and AHR repressor (AHRR) mRNA expression were analyzed in a cohort of 439 breast tumors, demonstrating a weak association between high AHR expression and age greater than fifty years and ERα-negative status, and HR-/ERBB2 breast cancer subtypes." (PMID 29320557, 2018). "The present results suggest that AHR expression levels could also be discriminant in patients with hormone receptor positive and negative breast cancers and also indicate that AhR is a target for breast cancer therapy." (PMID 29320557, 2018). "Meanwhile, another study using breast cancer cells demonstrated TCDD-induced binding of the AhR to the COX-2 promoter, suggesting that the coordinated recruitment of the AhR, p300, and histone H4 acetylation may lead to the activation of COX-2 expression through the classical (genomic) pathway." (PMID 29568008, 2018). "While these results give one pause when considering the use of AHR agonists in breast cancer, they may not preclude the use of agonists since metastasis, the most lethal step in carcinomas, requires both tissue invasion and migration." (PMID 29735912, 2018). "In addition, in breast carcinoma tissues, the H score of aromatase was significantly higher in AhR-positive areas than negative areas of the tumor." (PMID 29039776, 2017).
breast carcinoma (continued). "The same study showed that SR1 and a related AHR antagonist SR2 increase self-renewal capacity of breast cancer stem cells by upregulating LY6E which is a gene not directly involved in self-renewal but that can alter cell cycling and responses to growth factors." (PMID 27563312, 2016). "TNBC lines were selected for these studies primarily because no effective targeted therapeutic is yet available for this class of breast cancers and because we wanted to evaluate AHR signaling in the absence of its well-established interactions with the estrogen receptor." (PMID 26984638, 2016). "This study identified a new potential AI-treatment predictive marker in CYP1A2 rs762551 for early breast cancer events, and the results indicate that CYP1A2 rs762551 in combination with CYP19A1 rs4646 or AhR Arg554Lys may yield even better treatment prediction." (PMID 27029552, 2016). "Several recently published works, demonstrated that even in the absence of exogenous ligands, AHR is overexpressed and constitutively active in a variety of human and/or rodent tumors including breast cancer, lung adenocarcinoma, pancreatic and prostate cancer." (PMID 26392334, 2015). "Similar results were observed in MDA-MB-231 cells cotreated with omeprazole and the AHR antagonists 3′,4′-methoxy-α-naphthoflavone and 3′-methoxy-4′-nitroflavone, further confirming a role for the AHR in mediating the inhibitory effects of omeprazole on MDA-MB-231 breast cancer cell invasion." (PMID 25011475, 2014). "Overall, this work provides evidence against the simplified view of AF sensitivity, and suggests that AF could mediate growth inhibitory effects in ERα-positive and negative breast cancer cells, as well as cells with impaired AhR expression and signaling." (PMID 24885022, 2014). "Study on AhR showed that it can be a potential drug target for estrogen receptor (ER)-positive breast cancer and relatively non-toxic 6-methyl-1,3,8-trichlorodibenzofuran (MCDF) is a highly valuable agent to inhibit hormone responsive breast cancer growth in animal models." (PMID 25365309, 2014). "Our observation on the breast cancer cell lines was later confirmed by others who showed that infinite life-span cell lines had low levels of AhR mRNA compared to immortalized but non-malignant cell lines, which showed a 10-fold increase in AhR mRNA expression." (PMID 25068070, 2013). "Indeed, AHR agonists inhibited invasive and metastatic features, and colony formation, of breast cancer cells of various phenotypes, irrespective of ER, PR or HER-2 status." (PMID 21072210, 2010). "It is important to note, however, that AhR antagonism may not benefit all type of cancers as, as noted in the sections above, in a subset of diseases AhR has been shown to act as a tumor suppressor (i.e. ER+ breast cancer, androgen-sensitive prostate cancer, non-MYCN-amplified neuroblastoma)." (PMID 38807762, 2024). "Therefore, it is clear that DIM activity in breast cancer may be due, in part, to inhibitory AhR–ER crosstalk, but multiple growth inhibitory/cell death pathways impacting breast and other cancer cell lines induced by DIM are AhR-independent." (PMID 39339278, 2024). "Thus, we could not confirm the previous in vitro findings that AhR induces intratumoral aromatase in breast cancer, but due to the limited number of aromatase-positive tumors, these findings should be interpreted with caution." (PMID 34094928, 2021). "In order to gain an insight into the mechanisms by which elevated AhR expression influences cancer progression independent of exogenous ligand, this study aimed to identify the alterations of gene expression and possible molecular mechanisms by which AhR overexpression contributes to breast cancer." (PMID 24932473, 2014).